CRP (C-reactive protein)
Diseases named in the same sentence as CRP in open-access papers (continued):
Sharing a sentence is not in itself a finding about the gene and the disease.
myocardial infarction (continued). "Our findings are in line with human studies that found that risk of cardiovascular events, including myocardial infarction is associated with increased blood levels of inflammatory cytokines such as TNF-α and its receptors, adhesion molecules, and CRP." (PMID 22745783, 2012). "Serum levels of leptin, IL-6 and CRP were evaluated for 93 Acute Myocardial Infarction (AMI) patients and 102 control subjects." (PMID 22891684, 2012). "In patients with acute myocardial infarction, insulin also suppressed C-reactive protein (CRP) and serum amyloid A (SAA) by 40% within 24 h of the start of the insulin infusion while glucose concentrations rendered unchanged." (PMID 23497719, 2012). "The purpose of this study is to evaluate the importance of tenascin-C ( TNC), N-terminal pro brain natriuretic peptide (NT-proBNP) and C-reactive protein (CRP) on LV remodelling after myocardial infarction (MI)." (PMID 22383923, 2012). "C-reactive protein localizes the complement in human hearts during myocardial infarction, suggesting that CRP binds diseased muscle tissue, fixes complement and hence, triggers complement mediated inflammation that contributes to atheroma formation." (PMID 21760667, 2010). "The predictive power of NT-proBNP, CRP and Revised Cardiac Risk Index (RCRI) for the risk of PMCE (myocardial infarction, pulmonary oedema or cardiovascular death) were evaluated from a prospective cohort of 2054 elective major non-cardiac surgery patients." (PMID 19861299, 2010). "The direction of the association we found is consistent with the findings of a multi-city panel study of myocardial infarction survivors in Europe, where decrease in temperature predicted increase in the levels of CRP." (PMID 20653951, 2010). "Clinical heart failure and treatment with ACE-inhibitors were more common among those with highest peak CRP concentration, probably reflecting more extensive myocardial infarction." (PMID 19583836, 2009). "It is previously shown that CRP is elevated in cases of myocardial infarction, as CRP rises in response to various inflammatory stimuli, including tissue necrosis and myocardial infarction." (PMID 19503842, 2009). "Specific small-molecule inhibitors of CRP have recently been developed with the intent of mitigating cardiac damage during acute myocardial infarction." (PMID 19690638, 2007). "This inhibitor abrogated the increase in infarct size and cardiac dysfunction produced by injection of human CRP in a rat model of acute myocardial infarction." (PMID 19690638, 2007). "Additionally, a prospective study demonstrated that the albumin-CRP ratio, which integrates albumin and CRP, has superior predictive ability for in-hospital mortality in acute myocardial infarction patients compared to CRP or albumin alone." (PMID 41607462, 2026). "Mannitol prescription in patients with myocardial infarction and an elevated serum C-reactive protein level may be an effective and safe method to prevent delirium." (PMID 41010627, 2025). "Our findings further underscore the hypothesis that targeting CRP in the setting of acute myocardial infarction might minimize myocardial damage." (PMID 40080922, 2025). "It included 10,061 patients with a history of myocardial infarction and elevated ultrasensitive C-reactive protein (hsCRP ≥ 2 mg/L) who received canakinumab (50 mg, 150 mg or 300 mg) or placebo, administered subcutaneously every 3 months, with a median follow-up of 3.7 years." (PMID 41511355, 2025). "In patients with prior myocardial infarction and elevated CRP, the IL-1β inhibitor, canakinumab, reduced cardiovascular event risk and the levels of IL-6 and CRP but did not affect LDL cholesterol and showed a small increase in fatal infections." (PMID 40564905, 2025). "Furthermore, it was shown that screening individuals with acute myocardial infarction using nano-biochips derived from salivary proteins (such as C-reactive protein, myoglobin, and myeloperoxidase) was efficient." (PMID 40005360, 2025).
myocardial infarction (continued). "Plasma CRP levels rise within 48 h following myocardial infarction and inversely correlate with prognosis in acute coronary syndromes (ACS), suggesting that therapeutic CRP reduction may improve outcomes." (PMID 41511355, 2025). "Moreover, CRP apheresis appears to be a promising therapeutic target in patients with acute myocardial infarction, with ongoing larger randomized trials to evaluate the effect on hard clinical outcome parameters such as heart failure and mortality." (PMID 41303859, 2025). "The rs671 (A) allele was also linked to elevated plasma high-sensitivity C-reactive protein (hs-CRP) levels during the early phase of acute myocardial infarction, and serum C-reactive protein (CRP) was found as a prognostic biomarker of function and survival in ALS patients." (PMID 39290715, 2024). "Higher levels of CRP were associated with lower likelihood of LVT resolution in acute phase myocardial infarction; Anticoagulant therapy is still needed for thrombus in the chronic stage of myocardial infarction." (PMID 38811882, 2024). "Finally, the regulatory role of miR-150 on CRP levels was described in an acute myocardial infarction rat model." (PMID 38302506, 2024). "After more and more evidence emerged, that cardiovascular diseases (CVDs) such as ischemic stroke and acute myocardial infarction are related to inflammation, moderately elevated levels of CRP, so called high-sensitive CRP (hs-CRP), gained interest as a potential new biomarker for these diseases." (PMID 39176390, 2024). "Participants had a prior myocardial infarction (MI) and CRP levels greater than 2 g/L." (PMID 38525188, 2024). "In patients with myocardial infarction (MI), serum Chi3l1 levels greatly increase, which correlates with the levels of C-reactive protein, matrix metalloproteinase-9, and brain natriuretic protein; diastolic dysfunction; and long-term increased overall mortality." (PMID 39769202, 2024). "By dividing 10,061 atherosclerotic patients with prior myocardial infarction and a high-sensitivity C-reactive protein (hs-CRP) ≥2 mg/L in 39 countries into a placebo group and three different doses of canakinumab, administered subcutaneously every three months." (PMID 39399488, 2024). "The level of C-reactive protein (CRP) can reflect an inflammation status of the human body and indicate the potential risks of infection, chronic inflammatory disease (such as rheumatoid arthritis or lupus), heart disease, and a second heart attack." (PMID 37468977, 2023). "Additionally, the triad represented by increased CRP, IL-6, and TNF has been associated with a very high risk of mortality due to acute myocardial infarction." (PMID 38255650, 2023). "The level of plasma PCSK9 is positively correlated with hs-CRP in myocardial infarction patients." (PMID 36970356, 2023). "In addition, studies have demonstrated a correlation between higher levels of CRP and the severity of myocardial infarction." (PMID 37859889, 2023). "Thus, there was a distinct dose-response relationship between the CRP increase and the myocardial infarction damage." (PMID 37626775, 2023). "In the Canakinumab Anti-Inflammatory Thrombosis Outcomes Study (CANTOS), patients with recent myocardial infarction and elevated high sensitivity C-reactive protein were randomized between several doses of canakinumab (a monoclonal antibody against interleukin-1β) and a placebo." (PMID 36835906, 2023). "Serum CRP level is an independent factor for HF after acute myocardial infarction." (PMID 36966338, 2023). "This would call the sustainability of CRP apheresis in myocardial infarction into question." (PMID 36362673, 2022). "Chronic kidney disease activates vascular inflammatory processes and as consequence high levels of inflammatory biomarkers such as interleukin-6 (IL-6), C-reactive protein (CRP), and tumor necrosis factor (TNF) are associated with an increased risk of myocardial infarction and mortality." (PMID 35453821, 2022).
myocardial infarction (continued). "Indeed, preclinical studies have consistently demonstrated a convincing role for CRP, potentially via its activating isoforms, in directly amplifying tissue damage in rodent models of myocardial infarction." (PMID 36177015, 2022). "Promising evidence regarding the effect of immunomodulatory strategies in the setting of ACS is currently emerging, as Canakinumab demonstrated a reduction in mortality and hospitalization for HF in patients with a personal history of myocardial infarction and elevated CRP." (PMID 35888173, 2022). "The canakinumab anti‐inflammatory thrombosis outcomes (CANTOS) study has shown that antagonism of IL‐1β reduces recurrent myocardial infarction in patients with plasma C‐reactive protein (CRP) levels >2 mg/L, suggesting an important role for IL‐1β induced inflammation in CVD." (PMID 35833096, 2022). "In the small subgroup of COLCOT trial, a large (>65%) reduction in the C-reactive protein level occurred over the first 6 months after myocardial infarction in colchicine and control groups, but the difference between the changes in the groups was not significant." (PMID 35783861, 2022). "The cytokine storm associated with COVID-19 infection could also be responsible for elevations in CRP, which has been associated with increased risk of CVD and myocardial infarction even in healthy people." (PMID 35203644, 2022). "However, the elevation of traditional markers of inflammation such as CRP and WBC levels are also associated with an increased risk of heart failure and mortality after acute myocardial infarction." (PMID 35456255, 2022). "CANTOS was a multicenter, randomized, double-blind, placebo-controlled trial of 10,061 patients with a previous myocardial infarction, inflammatory atherosclerosis, and a persistent proinflammatory response—defined as a high-sensitivity CRP (hs-CRP) level over 2 mg/L." (PMID 35086565, 2022). "The CANTOS study was designed as a randomized, double-blind, placebo-controlled international large-scale multicenter clinical trial enrolling 10,061 patients with a history of myocardial infarction (MI) with elevated (>2 mg/L) hypersensitivity C-reactive protein (hsCRP) from 39 countries." (PMID 36703734, 2022). "Although the clinical observations were promising and the significant correlation between post-infarction CRP amount and myocardial infarct size was significantly lost in the treatment group, CAMI-1 cannot be regarded as being conclusive because it was not randomized." (PMID 35407379, 2022). "Recently, in the multicentre matched-control pilot study on CRP apheresis in Acute Myocardial Infarction (CAMI-1), there was a correlation between the CRP gradient between 12 and 32 hours after symptom onset and both myocardial infarct size and the extent of reduction in left ventricular function." (PMID 35192610, 2022). "In addition, another study found that SAA correlates to the size of the tissue injury that happened within the myocardial infarction and responded faster than CRP." (PMID 34745775, 2021). "Data from acute myocardial infarction (AMI) studies indicate that CRP levels may reflect the severity of the myocardial injury, and high CRP levels are associated with a poorer prognosis." (PMID 34356982, 2021). "The monomeric form of CRP (mCRP) originates from adissociation of the native pentameric form (nCRP) on the surface of activatedplatelets and damaged cells and can be found in the necrotic zones afteracute myocardial infarction and in atherosclerotic plaques." (PMID 35127146, 2021). "Additional markers (e.g. troponin-T, C-reactive protein, and N-terminal pro-B-type natriuretic peptide) have proven useful in patients with acute myocardial infarction (MI), heart failure or myocardial hypertrophy, but have been shown to carry little incremental predictive value for chronic CAD." (PMID 35187107, 2021).
myocardial infarction (continued). "Experimental studies have demonstrated that CRP promotes myocyte apoptosis, increases infarct size, and impairs infarct healing in a rat model; and overexpression exacerbates ventricular remodelling after myocardial infarction." (PMID 34571836, 2021). "Also, Lp(a) was shown to be positively correlated with interleukin (IL)‐6 and CRP after acute myocardial infarcts, indicating its involvement in immune and pro‐inflammatory responses." (PMID 34709671, 2021). "Increased C-reactive protein levels in the first 24–48 h after acute myocardial infarction may be a predictor for long-term HF development and mortality." (PMID 34356208, 2021). "In the present registry maximal troponin values were reached in myocardial infarction patients either on the day of presentation or on the following day, whereas CRP in myopericarditis patients usually increased significantly on the second and third day of hospitalization." (PMID 33886564, 2021). "Given this background, the CAMI-1 study was designed to test the hypothesis, whether specific depletion of CRP is a means to reduce myocardial infarct size in humans." (PMID 33778017, 2021). "Based on an average follow-up of 7.5 years, low serum albumin levels together with high CRP levels were shown to be associated with long-term adverse cardiac events (all-cause death and nonfatal myocardial infarction)." (PMID 33453709, 2021). "In addition, in a rat model of acute myocardial infarction, artificial injection of CRP increased infarct size and exacerbated cardiac insufficiency, whereas the use of CRP inhibitors eliminated this effect." (PMID 34212039, 2021). "Indeed, suPAR has been reported to provide prognostic information in patient with HF, but was also able to predict accurately all-cause mortality and recurrent myocardial infarction (MI) after primary myocardial ischemic event, whereas CRP failed in this indication." (PMID 34046195, 2021). "Aim of this pilot study was to explore the relationship between CRP concentration and myocardial infarct size and left ventricular function, to demonstrate the benefit of CRP reduction on these myocardial features and to evaluate the feasibility and safety of CRP apheresis." (PMID 33778017, 2021). "CRP apheresis as a targeted anti-inflammatory strategy is based on the current knowledge of the damaging role of complement activation in mediating neutrophil and monocyte recruitment in acute myocardial infarction." (PMID 33778017, 2021). "Elevated peak C-reactive protein (CRP) levels are associated with reduced LV ejection fraction (LVEF), more severe myocardial tissue injury, and worse outcome in the setting of acute myocardial infarction." (PMID 34884196, 2021). "The ability of elevated CRP, CA 19-9 and IL-6 to predict one-year mortality, in terms of ROC statistics, was comparable to the ability of low-density lipoprotein cholesterol and apolipoprotein B to predict myocardial infarction." (PMID 34572824, 2021). "In the CAMI-1 trial it was investigated whether specific depletion of CRP can reduce the size of myocardial infarction in humans." (PMID 33679775, 2021). "Due to the similar vascular pathophysiology of DCI and acute myocardial infarction or ischemic stroke, the serum CRP levels might have a prognostic value in acute phase after SAH." (PMID 32220241, 2020). "The diseased group in both genders showed CRP levels high enough to suffer various diseases such as heart attack, transient ischemic attack (TIA), peripheral nerve failure, and giant cell arthritis (mean ± SD: 15.20 ± 7.21, p < 0.01 compared with the high-level control group)." (PMID 32019214, 2020). "The CANTOS (for “canakinumab anti-inflammatory thrombosis outcome study”) trial evaluated the effect of treatment with canakinumab, an anti-IL-1β neutralizing monoclonal IgG1 antibody, in patients with a history of myocardial infarction and high circulating levels of C-reactive protein (CRP)." (PMID 33584721, 2020).
myocardial infarction (continued). "The Canakinumab Anti-inflammatory Thrombosis Outcome Study (CANTOS) found that canakinumab at a dose of 150 mg every three months reduced adverse cardiovascular events in patients with previous myocardial infarction and C-reactive protein (CRP) levels of more than 2 mg/L." (PMID 32550081, 2020). "CRP apheresis was applied in patients with ST-elevation myocardial infarction (STEMI) (CAMI-1 trial: “Selective depletion of C-reactive protein by therapeutic apheresis (CRP apheresis) in acute myocardial infarction”, DRKS ID: DRKS00008988)." (PMID 32932587, 2020). "In the following, we would like to suggest a theory of how CMV may lead to increased hepatic CRP production after myocardial infarction." (PMID 32537679, 2020). "The CAMI-1 trial tested the hypothesis whether specific depletion of CRP by CRP apheresis can reduce myocardial infarct size in humans." (PMID 32932587, 2020). "CRP promotes the formation of unstable plaques of coronary atherosclerosis, and triggers the rupture of vulnerable plaques, cause thrombosis in coronary arteries and lead to the occurrence of ACS and acute myocardial infarction (AMI)." (PMID 32532208, 2020). "Examples of diseases that can reliably be diagnosed through salivary analysis are pancreatic (miR-3679-5p and miR-940), lung (cytokines IL1RN, IL1B, CXCL10), and breast cancers (phenylalanine, tryptophan), as well as myocardial infarction (C-reactive protein, myoglobin, and myeloperoxidase)." (PMID 32019170, 2020). "For example, recent clinical trials found an anti-inflammatory Canakinumab, a monoclonal antibody for IL-1β, significantly reduced incidence of recurrent cardiovascular events as well as lung cancer in patients with previous myocardial infarction and elevated CRP." (PMID 31644575, 2019). "Hence, based on this animal model, 1,6-bis-PC was proposed as a promising CRP inhibitor with cardioprotective potential in acute myocardial infarction and possible neuroprotective effects in stroke." (PMID 31151201, 2019). "Serum levels of IL-6 increase after acute myocardial infarction, and since high IL-6 and C-reactive protein levels coincide with peak cardiac troponin, they could confirm the connection between inflammation and infarct size." (PMID 31205590, 2019). "But of course in that trial not only CRP (by 37%) but especially LDL cholesterol decreased (nearly by 50%) along with all the end-points: myocardial infarction (MI), stroke, arterial revascularization, hospitalization for unstable angina, or death from CV causes." (PMID 29467655, 2018). "In the massive Canakinumab Anti-inflammatory Thrombosis Outcomes Study (CANTOS), 10,061 patients with prior myocardial infarction and evidence of systemic inflammation as determined by elevated serum CRP were randomized to receive either placebo or canakinumab (50, 150, or 300 mg every 3 months)." (PMID 30459597, 2018). "The best model to predict MACE included: troponin I (OR=1.007 (CI 95 % 1.002–1.012), p=0.009), RPF (OR=1.136 (CI 95 % 1.001–1.288), p=0.048), CRP (OR=1.008 (CI 95 % 1.001–1.014), p=0.023) and history of myocardial infarction (OR=2.039 (CI 95 % 1.093–3.806), p=0.025)." (PMID 28229159, 2017). "However, CRP for example is increased in several other conditions such as myocardial infarction and trauma and rheumatologic diseases." (PMID 28235076, 2017). "Ridker and coworkers reported a significant reduction in the risk for myocardial infarction after aspirin administration in the highest quartile of baseline CRP levels, but not in the lowest quartile." (PMID 28190975, 2017). "In multivariable logistic regression, MACE was best predicted by troponin I (OR=1.007 (CI 95 % 1.002–1.012), p=0.009), RPF (OR=1.136 (CI 95 % 1.001–1.288), p=0.048), CRP (OR=1.008 (CI 95 % 1.001–1.014), p=0.023) and history of myocardial infarction (OR=2.039 (95 % CI 1.093–3.806), p=0.025)." (PMID 28229159, 2017).